MIR378D1 (microRNA 378d-1)
Synonyms: hsa-mir-378d-1; mir-378d-1
Gene: MicroRNA gene on chromosome 4 (5,923,275 to 5,923,328, reverse strand). Ensembl gene ENSG00000263631.
Diseases named in the same sentence as MIR378D1 in open-access papers:
MIR378D1 is named in the same sentence as 1 disease in open-access papers, as found by Europe PMC text mining. Sharing a sentence is not in itself a finding about the gene and the disease. The quoted sentences say what the papers report.
gastric cancer (1 paper, 2023). A primary or metastatic malignant neoplasm involving the stomach. "In this study, mGWAS-based studies localized four non-coding RNAs associated with gastric cancer prognosis, namely, MIR202HG (MIR202 host gene), MIR378D1, LINC02472, and LINC02310." (PMID 37894938, 2023).